FOXP3 (forkhead box P3)
Diseases named in the same sentence as FOXP3 in open-access papers (continued):
Sharing a sentence is not in itself a finding about the gene and the disease.
rectal cancer (23 papers, 2014 to 2025). A primary or metastatic malignant neoplasm that affects the rectum. "In summary FoxP3+ cells were associated with an improved prognosis in advanced rectal cancer." (PMID 27494875, 2016). "In HNSCC and rectal cancer, the prognostic relevance of FoxP3+ regulatory T cells can completely change in the presence of cellular inflammation." (PMID 35741089, 2022). "The present study shows that immunonutiriton prior to surgery provides similar CD4 and CD8 T cell counts and FOXp3 levels compared to standard nutrition in locally advanced rectal cancer patients." (PMID 36326418, 2022). "In the present study, we found a fall in degree of infiltration of T-regulatory FOXP3+ immune cells in the intratumor stroma of cancers from the right- to the left colon/rectum (excluding cases of irradiated rectum cancer)." (PMID 32316975, 2020). "In our neoadjuvantly treated rectal cancer cohort we found high numbers of FoxP3+ cells especially in the stromal compartment of pre-RCT biopsies." (PMID 27494875, 2016). "In conclusion, we were able to identify local immune escape mechanisms of rectal cancer, where the presence of Foxp3+ infiltration greatly influences a better prognosis." (PMID 24997850, 2014). "Similarly, rectal cancer patients with a lower infiltration of FOXP3+ T-cells in pretreatment biopsies responded better to neoadjuvant chemoradiation and had better prognosis." (PMID 37232754, 2023). "Therefore, we focused on CD8+ CTL and FoxP3+ cells spatial distribution in advanced rectal cancer patients." (PMID 27494875, 2016). "Increased staining for CD11b and FOXP3 was detected in poor responder patients compared to good responders, specifically in island of tumor budding, a rectal cancer poor prognostic factor." (PMID 25823653, 2015). "This was also supported in the context of rectal cancer where the location of CD8+ T cells and FoxP3+ Treg cells in distinct compartments (epithelium versus stroma) result in different prognostic responses." (PMID 35805132, 2022). "According to previous studies on rectal cancer, external beam radiation induces a significant decrease of inhibitory (FoxP3+) cells and modifies the CD8+/FoxP3+ ratio of TILs in the tumor and stromal tissue, leading to improved progression-free survival." (PMID 35158822, 2022). "Tissue microarrays from 154 rectal cancer resections were immunohistochemically double stained for CD8 and FoxP3." (PMID 35140715, 2022). "Given that few studies performed on rectal cancer patients, the TIL subtypes were only divided into two groups for analysis, one group was CD3+, CD8+ T cells and the other was FOXP3 + T cell." (PMID 31118034, 2019). "In conclusion, we show that Foxp3+ cell density in the tumour microenvironment prior to CRT did not predict tumour regression in locally advanced rectal cancer." (PMID 28177891, 2017). "Infiltration of the tumor stroma by T-regulatory FOXP3+ cells showed a significantly negative low correlation to CRP (Spearman’s rho –0.18, 95% CI from –0.32 to –0.05 for all non-irradiated and –0.24, 95% CI from –0.42 to –0.05 for non-irradiated rectal cancers." (PMID 32316975, 2020).
sarcoidosis (23 papers, 2012 to 2023). Sarcoidosis is a multisystemic disorder of unknown cause characterized by the formation of immune granulomas in involved organs. "IDO-expressing DCs and Foxp3+ Tregs have been implicated in the development of various infectious and autoimmune pathological conditions of the epithelium, including lichen planus, lupus vulgaris, sarcoidosis and infections caused by Mycobacterium leprae, Haemophilus ducreyi, UPEC and Leishmania sp." (PMID 24945497, 2014). "Early reports claimed that the frequency of FOXP3-expressing blood Tregs was decreased in sarcoidosis patients compared with control participants." (PMID 37520566, 2023). "Clusters 2, 7, and 12 (referred to as “CD4+ SAR-1”) were highly enriched CD4+FOXP3- clusters in the sarcoidosis samples." (PMID 35668129, 2022). "CD4+FOXP3- cells were the most abundant T cell type in sarcoidosis, accounting for 70.2% of T cells." (PMID 35668129, 2022). "A second population of CD4+FOXP3- cells was also enriched in the sarcoidosis samples (clusters 3, 8, and 4; referred to as “CD4+ SAR-2”)." (PMID 35668129, 2022). "The functional delineation of Foxp3+CD4+T cells into rTregs and mTregs based on CD45RA and FoxP3 expression had lead to the observations that mTregs were main suppressors in chronic inflammatory disease, sarcoidosis, liver cirrhosis and cancer." (PMID 29127350, 2017). "The dampening of Th17-driven immunopathology is believed to promote the generation of Foxp3+ Tregs, and this process is a novel target for the control of sarcoidosis and therapeutic surveillance." (PMID 26845566, 2016). "The fraction of FoxP3+ CD4+ T cells in BALF was significantly lower in patients with sarcoidosis compared to other DPLDs and HCs (median (IQR): 3.4% (2.1–4.8) versus 7.1% (4.4–12.6), P = 0.001 and versus 5.3% (4.4–7.0), P = 0.017)." (PMID 24882950, 2014). "IFN-γ+ Th17 cells were highly correlated with Th1 cells (N = 23, rho = 0.64, and P = 0.001), and the ratio of IFN-γ+ Th17/FoxP3+ CD4+ T cells was prominently increased in sarcoidosis." (PMID 24882950, 2014). "Later, the same group reported increased fractions of CD45RA−FoxP3bright CD4+ T cells in peripheral blood and CD4+ FoxP3+ cells in lymph nodes and granulomas of patients with active sarcoidosis." (PMID 24882950, 2014). "The ratio between IFN-γ+ Th17 cells and FoxP3+ CD4+ T cells is markedly raised in patients with sarcoidosis in our study." (PMID 24882950, 2014). "The ratio of IFN-γ+ Th17/FoxP3+ CD4+ T cells was considerably increased in sarcoidosis compared to other DPLDs or HC." (PMID 24882950, 2014). "Expression of CD27 and CD39 on FoxP3+ CD4+ T cells was higher in other DPLDs compared to sarcoidosis (P = 0.01 and P = 0.03, resp)." (PMID 24882950, 2014). "A recent study showed that IL‐10 producing B cells (or ‘‘B reg cells’’) were increased in sarcoidosis 17, resonating the findings of increased FoxP3 Treg cells in this condition." (PMID 24723379, 2014). "The mean fluorescence intensity (MFI) of Foxp3 was higher in Tregs of PBMCs from HCs (26169.1 ± 3258.3) compared to sarcoidosis patients (18347 ± 5958.8) (p < 0.05)." (PMID 24177566, 2013). "Other recent studies also support the immunosuppressive roles of VIP because VIP relieves collagen-induced arthritis and sarcoidosis by inducing CD4+CD25+Foxp3+ TReg cells from CD4+CD25− T cells." (PMID 22496728, 2012). "In conclusion, we have identified a set of inflammatory markers (sCD25, TNFR I and II) and Ki- 67 expression in sarcoidosis which may reflect suppressive capability of FOXP3+ Tregs in vivo, and therefore serve as indirect measures of Treg suppressive function." (PMID 38173720, 2023). "Indeed, a distinct CD4+FOXP3- cluster present exclusively in the sarcoidosis samples, with a Th1 phenotype marked by upregulation of IFNG and to a lesser degree CSF2 (GM-CSF), was identified." (PMID 35668129, 2022).
sarcoidosis (continued). "Furthermore, inhaled VIP administered in a clinical trial for sarcoidosis patients was found to significantly increase the numbers of CD4+CD127−CD25+ FOXP3+ T cells in the BAL." (PMID 33176790, 2020). "Thus, despite adequate Treg proportions and expression of FoxP3-downstream effector molecules, sarcoidosis-derived PB Tregs fail to suppress autologous Th cell responses." (PMID 26376720, 2015). "Sarcoidosis circulating Tregs displayed adequate expression of FoxP3, CD25 and CTLA4." (PMID 26376720, 2015). "Furthermore, CD25 and CTLA4 expression (downstream molecules of FoxP3) were significantly increased on PB CD25int-highFoxP3high Tregs of sarcoidosis patients compared with healthy controls." (PMID 26376720, 2015). "An increased ratio between IFN-γ+ Th17 cells and FoxP3+ CD4+ T cells may represent a corresponding feature of sarcoidosis." (PMID 24882950, 2014). "In the present study, the FoxP3+ fractions of CD4+ T cells in sarcoidosis were lower than in HC." (PMID 24882950, 2014). "Bronchoalveolar lavage fluid cells, from 30 patients with sarcoidosis, 18 patients with other diffuse parenchymal lung diseases, and 15 healthy controls, were investigated with flow cytometry for intracellular expression of FoxP3." (PMID 24882950, 2014). "Furthermore, we found a high degree of correlation between fractions of IFN-γ+ Th17 and Th1 cells, and the ratio of IFN-γ+ Th17/FoxP3+ CD4+ T cells was prominently increased in sarcoidosis compared to other DPLDs or HCs." (PMID 24882950, 2014). "This may indicate a strong Th1 immune response in sarcoidosis patients resulting in deviation of CD4+ T cell differentiation from FoxP3+ CD4+ T cells and plain Th17 cells into IFN-γ+ Th17 and Th1 cells." (PMID 24882950, 2014). "Therefore, we analyzed circulating CD25int-highFoxP3high Tregs of active sarcoidosis patients and healthy controls for expression of forkhead box P3 (FoxP3), CD25 and cytotoxic T lymphocyte antigen 4 (CTLA4) (three proteins pivotal for adequate Treg function) by flow cytometry." (PMID 26376720, 2015). "The balance between Th1, Th17, and FoxP3+ CD4+ T cell subsets in sarcoidosis remains unclear." (PMID 24882950, 2014). "Furthermore, as the MFI of Foxp3 was also lower in sarcoidosis patients, we hypothesize that Treg cell function in sarcoidosis patients may be impaired." (PMID 24177566, 2013). "Although recovery of T cells in the sarcoidosis samples appeared suboptimal, we observed that similarly to the skin, in BAL the majority of T cells were CD4+FOXP3-." (PMID 35668129, 2022). "The number of Treg cells is found to be decreased both in blood and BALF from sarcoidosis patients, with lower expression of FoxP3 in BAL cells, and treatment with prednisone induces elevated FoxP3 mRNA levels." (PMID 34868074, 2021). "The co-expression of FOXP3 and BPV E2 within the virus transformed cells adds an extra dimension to its potential role in the pathogenesis of sarcoids." (PMID 27160146, 2016). "Fractions of both Th17 cells and FoxP3+ CD4+ T cells were lower in sarcoidosis than in HC, and we found a highly elevated ratio between IFN-γ+ fractions of Th17 cells and FoxP3+ CD4+ T cells, possibly indicating an immune cell imbalance." (PMID 24882950, 2014). "In this study, we investigated the proportion of CD4+ T cell subsets expressing FoxP3 and, upon stimulation, IL17 or IFN-γ in patients with sarcoidosis, other DPLDs, and healthy control subjects." (PMID 24882950, 2014). "Fractions of BALF FoxP3+ CD4+ T cells and Th17 cells were lower in sarcoidosis compared to healthy controls." (PMID 24882950, 2014). "The fractions of FoxP3+ CD4+ T cells and Th17 cells were both lower in sarcoidosis compared to controls (P = 0.017 and P = 0.011, resp)." (PMID 24882950, 2014). "The aim of the study was to investigate the fractions of FoxP3+ CD4+ T cells, Th1, Th17, and IFN-γ+ Th17 cells in BALF and to assess the hypothesis about an imbalance between these subsets in sarcoidosis." (PMID 24882950, 2014).
sarcoidosis (continued). "The Th17 cell population in PBMCs was increased in sarcoidosis patients (1.61% ± 1.09%) compared with HCs (0.51% ± 0.43%) (p < 0.05), whereas CD4+ CD25high Foxp3+ Tregs were decreased in sarcoidosis patients (0.95% ± 0.91%) compared to HCs (2.68% ± 2.15%) (p < 0.05)." (PMID 24177566, 2013). "In sarcoidosis, fluorescence measurement further revealed compartment-specific differences of TIGIT, but not of PD-1 expression; TIGIT levels were significantly higher in T cells (including CD4+, CD8+, and FOXP3+) in the intergranulomatous area as compared to the granulomas (p < 0.05)." (PMID 30733837, 2019). "However, Foxp3 expression was lower in the patients who were stable than in those with active sarcoidosis who were not treated with corticosteroids." (PMID 26845566, 2016). "Our data supports this, and could also explain the ‘‘immunologically exhausted’’ nature of FoxP3 Treg cells observed in sarcoidosis 16 since these cells are functioning without the contribution from IL‐10 producing monocytes." (PMID 24723379, 2014). "In the sarcoidosis patients, the Th17 cell population in BALF (3.05% ± 1.87%) was increased compared with levels in PBMCs (1.61% ± 1.09%) (p < 0.05), while CD4+ CD25high Foxp3+ Tregs in BALF were increased (2.19% ± 1.71%) compared to levels in PBMCs (0.95% ± 0.91%) (p < 0.05)." (PMID 24177566, 2013).
thyroid cancer (23 papers, 2014 to 2025). "Our candidate gene studies, the first in Caucasians, and another one in Chinese patients, agree that FOXP3 rs3761548 A allele is associated with thyroid cancer predisposition." (PMID 39000267, 2024). "Some authors have shown an association between increased expression of Foxp3 and increased tumor aggressiveness in patients with thyroid cancer." (PMID 37345061, 2023). "Probably, the observed upregulation of FOXP3 in thyroid cancer cell is just the infiltration of FOXP3+ Treg cells in tumor microenvironment surveillance against cancer, which does not necessary reflect an increase of FOXP3 in Treg cells." (PMID 39000267, 2024). "Studies have also shown that the expression of FoxP3 in thyroid carcinoma cells is significantly related to the drug resistance phenotype of PTC to radioactive iodine therapy." (PMID 39534095, 2024). "Zhongqin Gong reported that inhibiting the expression of FoxP3 induced the apoptosis of thyroid carcinoma cells and suppressed their proliferation and migration." (PMID 39534095, 2024). "They correlated FoxP3 nuclear expression to the aggressiveness of differentiated thyroid carcinomas." (PMID 37563607, 2023). "In contrast, downregulating FOXP3 expression in thyroid cancer resulted in the downregulation of NF-κB subunit p65 and cyclin D1 concomitantly with the upregulation of caspase-3 levels." (PMID 26305693, 2015). "In addition, the miR-125b gene negatively regulates the expression of FoxP3, promotes autophagy in thyroid carcinoma, and enhances the therapeutic effect of cisplatin." (PMID 39534095, 2024). "miR-125b negatively governs Foxp3 expression via direct binding to Foxp3 3’ UTR, promoting autophagy and enhancing the efficacy of cisplatin in thyroid cancer." (PMID 38741041, 2024). "It is commonly accepted that thyroid cancer is linked to inflammation, which may explain the genetic and epigenetic associations of the present study with PTC predisposition, both of which could lead to reduced FOXP3 expression in blood cells, as other authors also reported for rs3761548 A allele." (PMID 39000267, 2024). "Therefore, FoxP3 may be an important intervention target for thyroid carcinoma treatment." (PMID 39534095, 2024). "In IHC study of FoxP3 involving thyroid cancer tissues (PTC and FTC) and benign thyroid tissue, FoxP3 expression was correlated with tumor aggressiveness, and tumor size was inversely correlated with FoxP3 expression." (PMID 36293435, 2022). "A negative link between miR-125b and Foxp3 expression was also confirmed in tissue samples and cell lines of thyroid cancer." (PMID 38741041, 2024). "Lower FOXP1, FOXP2 and higher FOXP3, FOXP4 levels could be identified in thyroid cancer tissues when compared with matched normal tissue." (PMID 36203616, 2022).
triple-negative breast carcinoma (23 papers, 2013 to 2026). An invasive breast carcinoma which is negative for expression of estrogen receptor (ER), progesterone receptor (PR), and human epidermal growth factor receptor 2 (HER2). "In another study, the variant genotype AA of FOXP3 was also positively associated with tumor size, in triple negative breast cancer." (PMID 27830498, 2016). "In addition, high levels of CD25+FoxP3+ tumor-infiltrating T-cells were associated with favorable prognosis in triple negative breast cancer patients." (PMID 27976733, 2016). "Gene expression profiling in RECQL knock-out (KO) MDA-MB-231 cells: Immunohistochemical analysis presented above shows that RECQL low tumors with T-cells infiltration (CD8+, FOXP3+, IL17, PDL1+, or PD1) are associated with triple negative breast cancers." (PMID 38134458, 2023). "The objective of this systematic review and meta-analysis was to determine the prognostic value of total tumor-infiltrating lymphocytes (TILs) and subtypes of TILs (CD4+, CD8+, and FOXP3+) in triple-negative breast cancer (TNBC)." (PMID 32131780, 2020). "However, a recent publication, asscessing FOXP3 expression in triple negative breast cancers, documented improved survival in patients with high levels of tumour infiltrating CD4+CD25+FOXP3+Tregs." (PMID 23320561, 2013). "The role of TILs as prognostic markers, especially CD8 and FOXP3 subtypes, has been evaluated in large studies, the majority focusing on ER−, HER2+, and triple negative breast cancers." (PMID 36598153, 2023). "Third, we apply the model to immunotherapy of triple-negative breast cancer and compare the simulations of spatial distribution of immune cells (e.g., CD8+ and FoxP3+ T cells) with our recent digital pathology quantitative analysis of patients’ specimens." (PMID 35867773, 2022). "In this study, we investigated CD20+ TILs in triple-negative breast cancer (TNBC) and their relationship with T lymphocyte subsets (CD4+, CD8+, CD25+, and FOXP3+), including their combined prognostic value using an immunohistochemical staining method." (PMID 33726701, 2021). "High levels of FOXP3+ T cells have been reported infiltrating invasive breast cancers and to be significantly increased in both HER2 positive and triple-negative breast cancers." (PMID 29390966, 2018). "We therefore studied the prognostic significance of CD8+ TILs and FOXP3+ TILs in residual tumors after neoadjuvant chemotherapy (NAC) and the alterations in these parameters before and after NAC in patients with triple-negative breast cancer (TNBC)." (PMID 26341640, 2015). "Similarly, in triple-negative breast carcinoma, a high CD8+ to FOXP3+ ratio in the tumor stroma correlated with improved overall survival." (PMID 41394821, 2025). "Cisplatin upregulated Foxp3 expression in HER2+ and triple-negative breast cancer (TNBC) cells." (PMID 37766222, 2023). "In this study, we discover immunological markers, such as tumor-infiltrating lymphocytes, CD8+, CD4+, FoxP3+, CD20+ lymphocytes, and their PD1 positivity or negativity, with the ability to predict benefits from eribulin within locally advanced or metastatic triple-negative breast cancer." (PMID 35814376, 2022). "We calculated the overall survival of non-metastatic, triple-negative breast cancer patients included in the METABRIC according to the ratio between the expression of CD8A and FOXP3 genes (CD8A/FOXP3 ratio)." (PMID 34362334, 2021).